TLR3 (toll like receptor 3)
Diseases named in the same sentence as TLR3 in open-access papers (continued):
Sharing a sentence is not in itself a finding about the gene and the disease.
hepatocellular carcinoma (continued). "The ability of HCV to suppress the expression of TLRs, including TLR3 and TLR7, could underlie its success in establishing a chronic infection that ultimately ends in cirrhosis and hepatocellular carcinoma." (PMID 24748896, 2014). "Through the study of hepatocellular carcinoma (HCC) patients caused by hepatitis B virus (HBV), TLR3 and TLR4 polymorphisms served as biomarkers of virus‐related tumors." (PMID 40727252, 2025). "Furthermore, TLR3/TLR4-TRIF exerts a crucial antiviral role in the initial stage of viral hepatitis, and when viral hepatitis progresses to serious complications such as cirrhosis and hepatocellular carcinoma, TLR3/TLR4-TRIF has been found to accelerate the disease process." (PMID 38694821, 2024). "Similarly, TLR3 was also downregulated in hepatocellular carcinoma." (PMID 34266404, 2021). "Multiple evident have shown the correlation of TLRs and apoptosis that stimulation of hepatocellular carcinoma (HCC) with poly(I:C) can promote apoptosis by activation of TLR3." (PMID 30127747, 2018). "It is well known from hepatoma cells, that HEV is recognized via pattern recognition receptors (PRRs) like RIG-I (DDX58) or TLR3, which activates the cascade of interferon signaling and provides immune responses to eliminate pathogens." (PMID 39546567, 2024). "TLR3, TLR7, and TLR8 protein were undetectable in most hepatoma cell lines and A549 epithelial cells as measured by surface antibody staining." (PMID 34831243, 2021). "Next, we addressed expression levels of the endosomal RNA sensors TLR3, TLR7, and TLR8 as well as the TLR3 adaptor TIR domain-containing adaptor protein 1 (TICAM1 or TRIF) in hepatoma cell lines and primary hepatocytes." (PMID 34831243, 2021). "TLR3 synthetic ligand poly-ICLC with sorafenib significantly reduces tumor growth, both in vitro and in vivo in hepatocellular carcinoma." (PMID 33072559, 2020). "Although downregulation of TLR3 gene expression has been mainly reported in patients infected with hepatitis C virus (HCV), the influence of TLR3 genotype on the risk of HCV infection, HCV-related cirrhosis, and/or hepatocellular carcinoma (HCC) remains to be determined." (PMID 28127569, 2017). "In the present study, we analyzed tissues of patients with human hepatocellular carcinoma (HCC) to determine the significance of the relationship between TLR3 expression and cell proliferation, apoptosis, hepatitis B virus infections, angiogenesis and prognosis." (PMID 25884709, 2015). "In order to accomplish the goal we compared our new hepatoma cell line LH86, which has intact TLR3 and RIG-I expression and responds to HCV by inducing IFN, with Huh7.5 cells which lack those features." (PMID 21695051, 2011). "Poly-ICLC, TLR3 agonists, combined with local nonlethal radiotherapy and local regional therapy, was safe and tolerable in patients with hepatocellular cancer (HCC)." (PMID 35745800, 2022). "The TLR3/IFN-β/MDA5/CXCL10 axis demonstrated by our study corroborates previous findings of the role of MDA5 in regulating CXCL10 expression in glomerular mesangial cells, brain microvascular endothelial cells, and hepatocellular carcinoma cells." (PMID 33387195, 2021). "Neither the PHH nor the tested epithelial and hepatoma cell lines upregulated IFN-β mRNA expression in a TLR3 mediated manner." (PMID 34831243, 2021). "This confirms that primary liver cells have a functional TLR3 pathway, which is not fully recapitulated by hepatoma cell lines." (PMID 34831243, 2021). "In HepG2 (liver carcinoma) cells and hepatocellular carcinoma cells, TLR3 induced apoptosis without an induction of pro-inflammatory cytokines." (PMID 30103522, 2018). "These hepatoma cells are stably reconstituted for TLR3 expression and signaling but are defective for RIG-I; they respond to HCV infection by upregulating RANTES and IP-10 expression through the TLR3 pathway." (PMID 29084253, 2017).
hepatocellular carcinoma (continued). "The role of TLR3 in hepatocellular carcinoma (HCC) with hepatitis B virus (HBV) infections is not well understood." (PMID 25983748, 2015). "TLR3 agonist Poly-ICLC (Hiltonol), which has been previously demonstrated to boost innate immune response in patients, was reported to impair the progression of hepatocellular carcinoma when combined with sorafenib, through the activation of NK and CD8+ T cells." (PMID 33147700, 2020). "The defect of TLR3 signaling in Marc-145 cells may be one reason that this cell type is permissive for PRRSV replication, which is reminiscent of another cell type, human hepatoma Huh7.5, with defects in RIG-I and other receptor signaling proteins that make it highly permissive to HCV infection." (PMID 34696285, 2021).
lung carcinoma (50 papers, 2008 to 2025). "We demonstrated that TLR3 activation in vitro induces apoptosis in lung cancer cell lines and, accordingly, that TLR3 expression is associated with caspase-3 activation in adenocarcinoma NSCLC specimens, both evaluated by immunohistochemistry." (PMID 32093313, 2020). "Together, these results support that polyI:C functions as a pro-apoptotic, anti-proliferative and anti-metastatic agent, which specifically targets TLR3 signaling pathway in susceptible lung cancer cells." (PMID 28427199, 2017). "We demonstrated heterogeneity of TLR3 protein levels in the subsets of lung cancer cell lines associated with differential susceptibility to polyI:C." (PMID 28427199, 2017). "Henceforth lung cancer cells which express low-to-medium levels of TLR3 protein, are referred to as ‘polyI:C-susceptible’, and 10 μg/mL polyI:C was applied for all subsequent studies unless otherwise stated." (PMID 28427199, 2017). "We found that FFAR2 was negatively associated with TLR2 and TLR3 in lung cancer." (PMID 37287005, 2023). "Since we utilized these two susceptible lung cancer cell lines to investigate the underlying mechanisms of polyI:C-mediated killing, it was rational to examine the loss-of-function of TLR3 in these cell lines to validate the specificity of polyI:C on the activation of TLR3 signalling." (PMID 28427199, 2017). "We have therefore uncovered the association of pro-inflammatory cytokine expression profiles with the TLR3-mediated apoptosis pathways, which could be utilised as indicators to predict therapeutic efficacy of lung cancers through their susceptibility to polyI:C treatment, with good prognosis." (PMID 28427199, 2017). "Lastly, exosomal RNA from mouse lung cancer cells has been shown to upregulate the expression of toll-like receptor 3 (TLR3) in type II alveolar epithelial cells through the NF-κB and MAPK pathways." (PMID 40575159, 2025). "Among these, the relevance of TLR3 expression on immune cells in dictating lung cancer progression has been demonstrated, indicating TLR3 as a prognostic marker for early NSCLC." (PMID 38776331, 2024). "Collectively, these results suggest that FFAR2 signaling functionally antagonizes lung cancer progression induced by TLR2 or TLR3 via the suppression of the AMPK-TAK1 signaling axis for the activation of NF-κB." (PMID 37287005, 2023). "Propionate, an agonist of FFAR2, antagonized TLR2- and TLR3-induced lung cancer migration, invasion, and colony formation by inhibiting the AMPK-TAK1 signaling axis for the activation of NF-κB." (PMID 37287005, 2023). "Recently, it has been reported that autophagy can facilitate TLR4- and TLR3-triggered migration and invasion of lung cancer cells through the promotion of TRAF6 ubiquitination." (PMID 37443143, 2023). "We found that propionate inhibited TLR2- and TLR3-induced lung cancer migration, invasion, and colony formation accompanied by the inhibition of the cAMP-AMPK-TAK1 signaling axis for the activation of NF-κB and the production of CCL2, IL-6, and MMP2 cytokines." (PMID 37287005, 2023). "Taken together, these results suggest that ARRB2 can functionally inhibit the migration, invasion, colony formation, and proliferation of lung cancer cells induced by TLR3 and TLR4 stimulation." (PMID 37443143, 2023). "TLR3 has also been considered as a favorable prognostic biomarker of lung cancer, either by activating apoptosis or promoting autophagy." (PMID 37112730, 2023). "In summary, our study identified negative regulation by propionate, which is an SCFA and recognized by FFAR2, in TLR2- and TLR3-induced lung cancer progression." (PMID 37287005, 2023). "TLR3 activation in vitro has been shown to induce apoptosis in the lung cancer cell lines Calu-3 (adenocarcinoma) and H460 (large cell carcinoma), and is associated with caspase-3 activation in human adenocarcinoma NSCLC tissue." (PMID 37112730, 2023).
lung carcinoma (continued). "In contrast, the down-regulation of FFAR2 in lung cancer did not attenuate the cAMP-AMPK-TAK1 signaling axis for the activation of NF-κB, thereby enhancing TLR2- and TLR3-induced lung cancer progression (right)." (PMID 37287005, 2023). "Altogether, our current data suggest that ARRB2 can negatively regulate lung cancer progression by inhibiting TLR3- and TLR4-induced autophagy." (PMID 37443143, 2023). "Our results also demonstrate that ARRB2 can negatively regulate the TRAF6-TAB2 signaling axis for NF-κB activation and the TRAF6-BECN1 signaling axis for autophagy induction, thereby attenuating lung cancer progression induced by TLR3 and TLR4." (PMID 37443143, 2023). "Taken together, these results suggest that FFAR2 antagonizes TLR2- and TLR3-induced lung cancer progression." (PMID 37287005, 2023). "We next explored the molecular mechanism by which FFAR2 signaling inhibited TLR2- and TLR3-induced lung cancer progression." (PMID 37287005, 2023). "For example, lung cancer microparticles (L-MPs) activated TLR3 and NLRP3 inflammasome, induced macrophages to release IL-1β, and thus promoted lung cancer development." (PMID 35413927, 2022). "In in vitro experiments, it has been found that TLR3 activation induces apoptosis of lung cancer cell lines." (PMID 35664309, 2022). "Taken together, our findings serve for a better understanding of the role of TLR3 in the development of lung cancer." (PMID 34094905, 2021). "The molecular mechanism is Toll-Like Receptor 3 (TLR3) agonists, and it was found that the activation of TLR3 in vitro can induce apoptosis in lung cancer cell lines." (PMID 33796026, 2021). "TLR3 has also been recognized as a favorable prognosis biomarker of lung cancer by activating apoptosis or promoting autophagy." (PMID 34094905, 2021). "On the other hand, Hiltonol mainly triggered MDA5 and TLR3 in H1299 cells, a lung cancer cell line which is apparently immutable and resistant to polyI:C." (PMID 33562773, 2021). "Several studies have demonstrated TLR3 expression in multiple neoplasia types including breast, prostate, and lung cancer." (PMID 33147700, 2020). "In a lung cancer model, TLR4 and TLR3 activation caused an induction of autophagy, which enhanced cytokine production and increased the migration and invasion of lung cancer cells." (PMID 32745353, 2020). "Here, we then showed that TLR3-mediated apoptosis of lung cancer cells indirectly contributes to the activation of immune response against tumors." (PMID 32093313, 2020). "In this study, we found that human lung cancer cell-released MPs trigger the TLR3 and NLRP3 inflammasome pathways in macrophages, leading to the secretion of IL-1β." (PMID 31649305, 2020). "The activation of NF-κB and MAPK signaling after TLR4 and TLR3 stimulation has been demonstrated to promote invasion of lung cancer cells." (PMID 33036630, 2020). "Two human lung cancer cell lines that express TLR3 —Calu-3 (adenocarcinoma) and H460 (large cell carcinoma)—were treated with a synthetic TLR3 agonist, Poly(I:C), to mimic the effects of viral dsRNAs in vitro." (PMID 32093313, 2020). "Our evidence of the prognostic role of TLR3 expression on lung cancer cells reveals the possibility to exploit TLR3 activation to induce cancer cells apoptosis, concurrently with immune activation." (PMID 32093313, 2020). "It has been reported that autophagy promotes TLR4- and TLR3-induced migration and invasion of lung cancer cells." (PMID 31620128, 2019). "For example, the strategy of activating TLR3 in lung cancer tumors appears to generate contradictory effects, inducing regressions in some tumors while conferring resistance in others 45,46." (PMID 31588231, 2019). "Our data indicate that TAR RNA-bearing exosomes activate the ERK1/2 cascade in association with EGFR and TLR3 to promote proliferation, migration, and invasion of HNSCC and lung cancer cells." (PMID 30389917, 2018).
lung carcinoma (continued). "For example, activation of TLR4 and TLR3 by LPS and polyinosinic–polycytidylic acid, respectively, induced autophagy in macrophages and lung cancer cells." (PMID 29752434, 2018). "We have now developed an automated immunostaining protocol and evaluated TLR3 expression in a cohort of human lung cancers." (PMID 30158588, 2018). "PolyI:C stimulation significantly increased TLR3 expression in A549 and NCI-H292, which prompted us to further study the impact of differential engagement of polyI:C with TLR3 on the different lung cancer cell lines." (PMID 28427199, 2017). "Taken together, polyI:C alone provoked apoptosis of lung cancer cells that express low-to-medium levels of functional TLR3 protein." (PMID 28427199, 2017). "A recent study has shown that autophagy facilitates toll-like receptor (TLR) 4 (TLR4)- and TLR3-triggered migration and invasion of lung cancer cells through promoting TRAF6 ubiquitination." (PMID 29326710, 2017). "Activation of TLR3 by polyI:C in lung cancer cells triggers inflammation and inhibits growth through production of inflammatory cytokines, anti-proliferative proteins and upregulation of caspase-dependent apoptosis." (PMID 28427199, 2017). "For example, TLR ligands demonstrated anti-apoptotic and metastatic effects in human lung cancer cells and induced proliferation in human myeloma cells (TLR3)." (PMID 27941651, 2016). "Besides, TLR3 contributes to the establishment of a pro-tumorigenic inflammatory microenvironment to promote lung cancer progression via NLRP3 inflammasome activation and subsequent IL-1β release." (PMID 41293166, 2025). "In addition, a previous report has shown that autophagy can facilitate TLR4- and TLR3-triggered migration and invasion of lung cancer cells by promoting TRAF6 ubiquitination." (PMID 37443143, 2023). "Collectively, our results strongly suggest the FFAR2 signal might antagonize TLR2- and TLR3-induced lung cancer progression via suppression of the cAMP-AMPK-TAK1 signaling axis for the activation of NF-κB." (PMID 37287005, 2023). "In this study, we demonstrated that ARRB2, a multifunctional cellular adaptor protein capable of regulating cellular signaling pathways, could functionally regulate lung cancer progression induced by TLR3 and TLR4 through inhibition of NF-κB and autophagy." (PMID 37443143, 2023). "Notably, ARRB2-knockout (ARRB2KO) lung cancer cells exhibited marked enhancements of cancer migration, invasion, colony formation, and proliferation in response to TLR3 and TLR4 stimulation." (PMID 37443143, 2023). "In addition, the activation of TLR2, TLR3, and TLR4 was functionally implicated in lung cancer proliferation, migration, and invasion." (PMID 37287005, 2023). "In terms of function aspects, ARRB2KO lung cancer cells showed marked enhancements of autophagy and cancer progression including migration, invasion, colony formation, and proliferation in response to TLR3 and TLR4 stimulation." (PMID 37443143, 2023). "TLR3 has been regarded as a tumor suppressor-related factor in many lung cancer studies." (PMID 35664309, 2022). "Furthermore, it was demonstrated that TLR3-dependent M1 induction was effective in murine lung cancer models." (PMID 34181042, 2022). "The exact mechanism needs to be further investigated, but one in vitro study showed that the TLR3 signaling pathway might play a role in HPV-inducing lung cancer." (PMID 36389785, 2022). "Like TLR2, TLR3 also has conflicting roles in lung cancer as either pro- or anti-tumor receptors." (PMID 36389785, 2022). "Additionally, a reduction in overall survival was observed in lung cancer patients with high levels of both TLR3 and neutrophil infiltration." (PMID 34830787, 2021). "Furthermore, they found a correlation between the level of TLR3 in adjacent tissue to lung cancer with the presence of neutrophils." (PMID 34830787, 2021).